ENSG00000254673 (novel protein)
Gene: Protein-coding gene on chromosome 8 (43,018,424 to 43,077,334, forward strand). Ensembl gene ENSG00000254673.
Genetic constraint (gnomAD): Missense variants: 22 observed, 41.42 expected, observed/expected ratio (o/e) 0.53, 90% interval 0.38 to 0.76. Synonymous variants: 13 observed, 16.19 expected, observed/expected ratio (o/e) 0.8, 90% interval 0.52 to 1.28.